OTUD3 (OTU deubiquitinase 3)
Diseases named in the same sentence as OTUD3 in open-access papers (continued):
Sharing a sentence is not in itself a finding about the gene and the disease.
lung carcinoma (continued). "Collectively, our data indicated that OTUD3 plays an oncogenic role in lung cancer cells and its regulation of tumor growth is indispensable on its DUB activity." (PMID 31266968, 2019). "To further investigate the role of OTUD3 in human lung cancer, we knocked down endogenous OTUD3 in H1299 and A549 cells." (PMID 31266968, 2019). "Taken together, these data suggest that GRP78 is a specific substrate of OTUD3 in lung cancer cells." (PMID 31266968, 2019). "In addition, CHIP was identified as the E3 ubiquitin ligase of OTUD3, which can block OTUD3/GRP78 by accelerating the degradation of OTUD3 through ubiquitination, thus inhibiting the malignant progression of lung cancer." (PMID 41050073, 2025). "Our previous study showed that OTUD3 stabilized the GRP78 protein in lung cancer cells." (PMID 38539203, 2024). "In addition, when OTUD3 was knocked down, the growth of lung cancer cells was less affected by Rolapitant." (PMID 38539203, 2024). "This implies that targeted inhibition of OTUD3 may be a potential strategy for the treatment of lung cancer." (PMID 37369659, 2023). "Previous studies have shown that Bip is the target protein of OTUD3 in lung cancer cells." (PMID 37107185, 2023). "The deubiquitylase OTUD3 was reported to promote lung tumorigenesis by stabilizing oncoprotein GRP78, implying that inhibition of OTUD3 may be a therapeutic strategy for lung cancer." (PMID 37369659, 2023). "In lung cancer, OTUD3 interacts with GRP78, inhibiting cell growth and migration." (PMID 38288086, 2023). "In addition, Carboxyl terminus of Hsc70-Interacting Protein (CHIP) was found as a negative regulator of OTUD3, and it suppressed the metastasis of lung cancer." (PMID 32882786, 2020). "Moreover, OTUD3 is highly expressed in human lung cancer tissues and its higher expression correlates with poorer survival of patients." (PMID 31266968, 2019). "Collectively, our results reveal a previously unappreciated pro-oncogenic role of OTUD3 in lung cancer and indicate that deubiquitylases could elicit tumor-suppressing or tumor-promoting activities in a cell- and tissue-dependent context." (PMID 31266968, 2019). "OTUD3 maintained GRP78 stability, leading to lung cancer cell growth and tumorigenesis in vitro and in vivo, even though the precise mechanisms that OTUD3 plays opposite role in different cancers and elevate expression in lung cancer still need further investigation." (PMID 31266968, 2019). "In order to assess whether OTUD3 could influence tumorigenesis in the tumor stroma, a mouse lung cancer cell line LLC was used to orthotopically transplant into WT or OTUD3 KO mice, as well as WT or OTUD3 TG mice." (PMID 31266968, 2019). "In lung cancer, CHIP stabilizes OTUD3 to suppress metastasis, while in prostate cancer, it enhances sensitivity to enzalutamide and abiraterone by degrading AR/AR-V7." (PMID 39075053, 2024). "OTUD3 interacts with the glucose-regulated protein GRP78 to deubiquitinate and stabilize GRP78, thereby inhibiting lung cancer cell growth and migration." (PMID 37829187, 2023). "OTUD3 facilitates PTEN-related tumor suppressive responses and inhibits breast tumorigenesis, while in lung cancer, OTUD3 promotes tumorigenic phenotypes by stabilizing GRP7853,54." (PMID 35233061, 2022). "In contrast to the downregulation of GRP78 stability and the suppression of tumor metastasis by GP78, OTUD3 enhances GRP78 stability, leading to the growth of lung cancer cells and contributing to tumorigenesis." (PMID 35661704, 2022). "OTUD3 plays an oncogenic role in lung cancer cells and promotes the development of lung cancer by directly interacting with GRP78, where OTUD3 deubiquitylates GRP78 and maintains GRP78 stability in vitro and in vivo." (PMID 33743739, 2021). "Knockdown of OTUD3 results in a decrease in the level of GRP78 protein, suppression of cell growth and migration, and tumorigenesis in lung cancer." (PMID 31266968, 2019).
lung carcinoma (continued). "The interaction between OTUD3 and GRP78 observed in lung cancer H1299 cells was hardly detected in MCF7 cells." (PMID 31266968, 2019). "In lung cancer, OTUB1 triggered lung cancer development by inhibiting RAS monoubiquitination; OTUB2 stabilized U2AF2 through the AKT/mTOR signaling pathway to promote the Warburg effect and tumorigenesis; and OTUD3 stabilized GRP78 to augment the malignancy." (PMID 40469292, 2025). "OTUD3, regulated by CHIP, impacts lung cancer invasion and metastasis." (PMID 38288086, 2023). "Given the role of OTUD3 as a deubiquitinase and its function in stabilizing GRP78 through deubiquitylation in lung cancer cells, we hypothesized that OTUD3 might deubiquitinate ACTN4 and stabilize it." (PMID 34380780, 2021). "Our data have indicated that OTUD3 fails to regulate PTEN stability in lung cancer whereas casting its role in mediating GRP78 deubiquitylation." (PMID 31266968, 2019). "We then investigated the correlation between OTUD3 and GRP78 in human lung cancer tissues." (PMID 31266968, 2019). "We found that GRP78 can be ubiquitylated in lung cancer cells and ectopic expression of WT, but not C76A OTUD3, reduced GRP78 ubiquitylation in cells." (PMID 31266968, 2019). "We found that OTUD3 colocalized with GRP78 in the cytoplasm (especially in ER) but not colocalized with PTEN in lung cancer cells." (PMID 31266968, 2019). "The deubiquitylase OTUD3 plays a suppressive role in breast tumorigenesis through stabilizing PTEN protein, but its role in lung cancer remains unclear." (PMID 31266968, 2019). "On the contrary, a related study reported that OTUD3 may act as an oncogene in HCC and lung cancer." (PMID 41050073, 2025). "Mechanistically, OTUD3 could not maintain the stability of PTEN proteins, but OTUD3 could promote lung cancer growth and metastasis by deubiquitinating and stabilizing the glucose regulatory protein GRP78." (PMID 41050073, 2025). "Furthermore, in lung cancer, OTUD3 fails to regulate PTEN and, in contrast, maintains the stability of the oncoprotein GRP78 (glucose-regulated protein 78-kDa), showing the tumor tissue complexity of the functional role of played by a given deubiquitinase." (PMID 36385557, 2022).
hepatocellular carcinoma (9 papers, 2019 to 2025). A malignant tumor that arises from hepatocytes. "Another article, however, revealed that OTUD3 acts as a tumor suppressor in hepatocellular carcinoma while simultaneously enhancing the sensitivity of liver cancer cells to sorafenib treatment." (PMID 40607251, 2025). "OTUD3 also influences hepatocellular carcinoma metastasis by mediating ACTN4 deubiquitination." (PMID 38288086, 2023). "OTUD3 mediates Alpha-actinin 4 ACTN4 deubiquitination in HCC to stabilize it and promote hepatocellular carcinoma cell growth and metastasis." (PMID 37829187, 2023). "OTUD3 promotes lung tumorigenesis by stabilizing GRP78, while it stabilizes ACTN4 to drive hepatocellular carcinoma progression and metastasis." (PMID 38351178, 2024). "The accurate function of OTUD3 in hepatocellular carcinoma (HCC) progression remains elusive." (PMID 34380780, 2021). "To further validate the different roles of OTUD3, we firstly evaluated the correlation between OTUD3 and PTEN in hepatocellular cancer (n = 73), colon cancer (n = 71), cervical cancer (n = 30), and lung adenocarcinoma (n = 85)." (PMID 31266968, 2019). "Even though OTUD3 acts as an oncogene in small cell lung cancer and hepatocellular cancer, its role in CRC has not been reported." (PMID 38351178, 2024).
diabetes (5 papers, 2020 to 2023). "The OTUD3 c.863G>A (rs78466831) mutation was identified in the obesity and diabetes family, a mutation that reduces the stability and catalytic activity of OTUD3." (PMID 37829187, 2023). "GSEA analysis showed that OTUD3 loss-of-function-associated genes scored high in diabetes, PPAR signaling pathway, glycolipid metabolism, and fatty acid degradation." (PMID 37829187, 2023). "It is possible that mutations in specific amino acids in OTUD3 lead to changes in protein conformation, which in turn leads to a much higher risk of developing diabetes." (PMID 37829187, 2023). "Several recent studies have shown that OTUD3 is associated with many human and animal diseases, such as innate immunity, inflammation, tumors, diabetes, and clinical mastitis in cows." (PMID 37829187, 2023). "Recently, a study showed that OTUD3 is an important regulator of glucose and lipid metabolism, and OTUD3 insufficiency is associated with obesity and a higher risk of diabetes." (PMID 37369659, 2023). "A novel, rare OTUD3 c.863G>A (rs78466831) in humans has been reported associated with diabetes, but the prevalence and clinical characteristics of T2DM patients with rs78466831 have not been reported before." (PMID 36531510, 2022). "In addition, we identified nine genes (CABIN1, CKS1B, C19orf60, SDR39U1, SLC31A1, DNAJA4, ZC3H8, OTUD3 and UBALD1) not previously associated with diabetes, but that are known to be involved in processes potentially linked to β-cell dysfunction, such as cell turnover, oxidative stress and ER stress." (PMID 33575641, 2020).
ovarian tumor (5 papers, 2020 to 2024). "OTUD3 contains an ovarian tumor (OTU) domain and a ubiquitin-associated (UBA) domain." (PMID 37369659, 2023). "OTU deubiquitinase 3 (OTUD3) binds to the ovarian tumor-related protease family, PTEN protector." (PMID 36727069, 2022). "Ovarian tumor domain-containing protein 3 (OTUD3), which is a key OTU (ovarian tumor protease) family deubiquitylase, plays important roles in a variety of cancers." (PMID 38539203, 2024). "Thus, Pearson correlation analysis between the expression level of B4GALT5 and OTU (ovarian tumour) family deubiquitinases (OTUB1, OTUB2, OTUD1, YOD1, OTUD3, OTUD4, OTUD7B) was performed." (PMID 36611197, 2023).
viral infection (5 papers, 2022 to 2025). "It seems that at resting states, the levels of MAVS-K63-linked ubiquitination remain low by OTUD3, while upon viral infection, OTUD3 is inactivated by SIRT1-mediated K129 deacetylation, allowing for the buildup of K63-linked ubiquitination of MAVS for its activation." (PMID 35795661, 2022). "However, since the acetylation level of OTUD3 is reduced upon viral infection, the cGAS/STING axis will respond to partially blocked DNA viruses to prevent excessive anti-DNA viral responses." (PMID 41050073, 2025). "However, since the acetylation level of OTUD3 is reduced upon viral infection, the RLR/MAVS axis will undergo partial activation in response to RNA viruses and initiate an anti-RNA virus response." (PMID 41050073, 2025). "OTUD3 acetylation would be removed upon virus infection, and the DUB activity would be blocked." (PMID 35283827, 2022). "Therefore, OTUD3 is controlled to timely response to virus infection." (PMID 35283827, 2022). "During viral infection, SIRT1 deacetylates OTUD3, thereby rapidly inactivating OTUD3 and providing effective innate anti-RNA virus immunity." (PMID 37829187, 2023). "Upon viral infection, sirtuin 1 (SIRT1) is recruited to deacetylate OTUD3, leading to the inactivation of OTUD3, which relieves MAVS suppression." (PMID 36385557, 2022).
cervical cancer (4 papers, 2019 to 2024). A primary or metastatic malignant neoplasm involving the cervix. "Collectively, these results suggest that OTUD3 is a bona fide suppressor of tumor growth and metastasis events in colon cancer, liver cancer, and cervical cancer." (PMID 31266968, 2019).
colon carcinoma (4 papers, 2019 to 2024). "MiR-32 also inhibits the expression of OTUD3 and promotes cell proliferation and motility and inhibits apoptosis in colon cancer cells." (PMID 37829187, 2023). "Similarly, MicroRNA 32 (miR-32) can directly target the 3′-untranslated region (3′-UTR) of OTUD3 to inhibit OTUD3 expression, which can promote proliferation and motility of colon cancer cells and inhibits apoptosis." (PMID 37829187, 2023). "We first observed that protein and mRNA levels of USP11, but not any other known PTEN DUBs (such as HAUSP, USP13, and OTUD3), were markedly lower in isogenic PTEN-null (PTEN-/-) HCT116 colon carcinoma cells compared to WT parent (PTEN+/+) or heterozygous (PTEN+/-) cells." (PMID 30733438, 2019).
esophageal cancer (4 papers, 2021 to 2025). A primary or metastatic malignant neoplasm involving the esophagus. "As indicated by previous study, downregulation of OTUD3 was associated with poor prognosis in patients with esophageal cancer." (PMID 38246894, 2024). "As the upstream regulator of OTUD3, we found that nuclear FOXO1 expression positively correlated with OTUD3 expression in esophageal cancer tissues and was significantly associated with the smoking behavior of patients." (PMID 34853315, 2021). "Significantly, the IHC staining and correlation analysis showed that OTUD3 positively correlated with ZFP36 expression levels but was reversely associated with VEGF-C expression levels in the 228 esophageal cancer specimens." (PMID 34853315, 2021). "Moreover, correlation analysis indicated that the smoking behavior and low OTUD3 expression were significantly associated with LN metastasis of esophageal cancer." (PMID 34853315, 2021). "Importantly, patients with combined low OTUD3 and high VEGF-C expression suffered the worse RFS and OS, especially in the heavy-smoking patients, further suggesting that the OTUD3/VEGF-C axis was indeed associated with poor clinical outcomes of esophageal cancer." (PMID 34853315, 2021). "By contrast, the CM from OTUD3-silencing esophageal cancer cells significantly increased the migration and tube formation of LECs." (PMID 34853315, 2021). "Here we show that nicotine-induced OTUD3 downregulation correlates with lymphangiogenesis, LN metastasis, and poor prognosis in smoking esophageal cancer patients." (PMID 34853315, 2021). "We further assessed the clinical significance of OTUD3 expression in the 228 paraffin-embedded esophageal cancer specimens." (PMID 34853315, 2021). "Conversely, silencing of OTUD3 decreased ZFP36 in esophageal cancer cells, and this effect was abolished under the treatment of proteasome inhibitor MG132." (PMID 34853315, 2021). "Here we show that OTU domain-containing protein 3 (OTUD3) is downregulated by nicotine and correlates with poor prognosis in heavy-smoking esophageal cancer patients." (PMID 34853315, 2021). "In studies on human esophageal cancer, OTUD3 directly interacted with ZFP36 and stabilized the ZFP36 protein by cleaving the K48-type polyUb chain, which subsequently promoted the degradation of vascular endothelial growth factor-C (VEGF-C) mRNA to inhibit lymphatic metastasis." (PMID 41050073, 2025). "It would be of great significance to further explore whether these proteins contribute to the tumor-suppressive role of OTUD3 in esophageal cancer." (PMID 34853315, 2021). "Finally, we assessed the OTUD3/ZFP36/VEGF-C axis’s clinical relevance in esophageal cancer specimens." (PMID 34853315, 2021). "Notably, OTUD3 was substantially decreased under nicotine exposure in esophageal cancer cells and heavy-smoking patient specimens." (PMID 34853315, 2021). "We overexpressed ZFP36 in nicotine-treated or OTUD3-silencing esophageal cancer cells." (PMID 34853315, 2021). "Notably, nicotine potently decreased ZFP36 expression in esophageal cancer cell lines and tumors, and these effects were abrogated by OTUD3 overexpression, suggesting that OTUD3 mediated the nicotine-induced ZFP36 downregulation." (PMID 34853315, 2021). "Therefore, it would be of great significance to investigate whether OTUD3 is downregulated and plays a critical role in e-cigarette-using esophageal cancer patients in the future." (PMID 34853315, 2021). "Low OTUD3 expression significantly correlated with clinicopathological characteristics, including tumor size (P < 0.001), LN metastasis (P = 0.002), pathological grades (P = 0.04), and clinical stages (P < 0.001), indicating a reverse correlation with esophageal cancer malignancy." (PMID 34853315, 2021).
esophageal cancer (continued). "Notably, ectopic expression of OTUD3 robustly prohibited the lymphangiogenesis and LN metastasis induced by nicotine, suggesting that reduction of OTUD3 was indispensable for nicotine-induced lymphatic metastasis in esophageal cancer." (PMID 34853315, 2021). "Downregulation of OTUD3 expression by Nicotine in esophageal cancer leads to downregulation of ZFP36, which induces VEGF-C production and promotes lymphatic metastasis in esophageal cancer." (PMID 37829187, 2023). "The PLAs and dual-IF staining revealed that OTUD3 and ZFP36 colocalized in the cytoplasm of esophageal cancer cells." (PMID 34853315, 2021). "Downregulation of OTUD3 and ZFP36 is essential for nicotine-induced VEGF-C production and lymphatic metastasis in esophageal cancer." (PMID 34853315, 2021). "However, the role of OTUD3 in smoking-mediated esophageal cancer progression remains unclear." (PMID 34853315, 2021). "Specifically, nicotine activated the PI3K/AKT signaling through the alpha 7 nAChR to inhibit FOXO1 activity and downregulate OTUD3 expression, leading to inhibition of VEGF-C mRNA decay and increase of VEGF-C paracrine secretion in esophageal cancer cells." (PMID 34853315, 2021). "Taken together, we here show that nicotine-mediated OTUD3 downregulation facilitates ZFP36 protein degradation and inhibits VEGF-C mRNA decay, leading to robust tumor-induced lymphangiogenesis and lymphatic metastasis in esophageal cancer." (PMID 34853315, 2021). "Interestingly, our recent RNA-seq analysis showed that OTUD3 was the most significantly regulated DUB gene (log2Fc > 1, P < 0.05) by CSE in esophageal cancer cells." (PMID 34853315, 2021). "Importantly, low expression of OTUD3 significantly predicted poorer tumor relapse-free survival (RFS) and overall survival (OS) in esophageal cancer patients, and this effect was more significant in the heavy-smoking patients than those in non-smokers." (PMID 34853315, 2021). "Consistently, CSE treatment downregulated the OTUD3 mRNA and protein expression in multiple esophageal cancer cell lines but not in the normal esophageal epithelial cell (NEEC)." (PMID 34853315, 2021). "OTUD3 and ZFP36 were potently downregulated, while VEGF-C was elevated in the freshly collected esophageal cancer samples from the heavy-smoking patients compared to those from non-smokers, suggesting a significant relevance of the OTUD3/ZFP36/VEGF-C axis in primary tumors." (PMID 34853315, 2021). "Moreover, silencing of FBXW7 inhibited polyubiquitination of ZFP36, increased ZFP36 protein expression, and reduced VEGF-C expression in OTUD3-silencing esophageal cancer cells, suggesting that downregulation of FBXW7 rescues the effects of OTUD3 depletion in ZFP36 and VEGF-C expression." (PMID 34853315, 2021). "This study establishes that the OTUD3/ZFP36/VEGF-C axis plays a vital role in nicotine addiction-induced lymphatic metastasis, suggesting that OTUD3 may serve as a prognostic marker, and induction of the VEGF-C mRNA decay might be a potential therapeutic strategy against human esophageal cancer." (PMID 34853315, 2021).